SLC29A4 (solute carrier family 29 member 4)
Description:
Electrogenic voltage-dependent transporter that mediates the transport of a variety of endogenous bioactive amines, cationic xenobiotics and drugs. Utilizes the physiologic inside-negative membrane potential as a driving force to facilitate cellular uptake of organic cations. Functions as a Na(+)- and Cl(-)- independent bidirectional transporter. Substrate transport is pH-dependent and enhanced under acidic condition, which is most likely the result of allosteric changes in the transporter structure. Implicated in monoamine neurotransmitters uptake such as serotonin, dopamine, adrenaline/epinephrine, noradrenaline/norepinephrine, histamine and tyramine, thereby supporting a role in homeostatic regulation of aminergic neurotransmission in the central nervous system. Also responsible for the uptake of bioactive amines and drugs through the blood-cerebrospinal fluid (CSF) barrier, from the CSF into choroid plexus epithelial cells, thereby playing a significant role in the clearance of cationic neurotoxins, xenobiotics and metabolic waste in the brain (By similarity). Involved in bidirectional transport of the purine nucleoside adenosine and plays a role in the regulation of extracellular adenosine concentrations in cardiac tissues, in particular during ischemia. May be involved in organic cation uptake from the tubular lumen into renal tubular cells, thereby contributing to organic cation reabsorption in the kidney. Also transports guanidine.
Synonyms: PMAT; ENT4; FLJ34923
Tractability: Antibody: UniProt places it where antibodies can reach, with high confidence; its Gene Ontology location is reachable by antibodies, with high confidence; UniProt predicts a signal peptide or a membrane-spanning region.
Target class: Electrochemical transporter; SLC28 and SLC29 families of nucleoside transporters; SLC29 Facilitative nucleoside transporter family; Transporter; SLC superfamily of solute carriers
Gene: Protein-coding gene on chromosome 7 (5,274,369 to 5,307,194, forward strand). Ensembl gene ENSG00000164638.
Subcellular location: Cell membrane; Apical cell membrane
Subcellular location (Human Protein Atlas): Cytokinetic bridge; Microtubules
Pathways (Reactome):
Transport of small molecules: Transport of nucleosides and free purine and pyrimidine bases across the plasma membrane
Gene Ontology:
Molecular function: efflux transmembrane transporter activity; monoamine transmembrane transporter activity; neurotransmitter transmembrane transporter activity; transmembrane transporter activity; monoatomic cation transmembrane transporter activity; nucleoside transmembrane transporter activity
Biological process: adenosine transport; dopamine uptake; epinephrine uptake; export across plasma membrane; histamine transport; histamine uptake; neurotransmitter transport; neurotransmitter uptake; norepinephrine uptake; serotonin uptake; transmembrane transport; cellular detoxification; monoatomic cation transmembrane transport; transport across blood-brain barrier; nucleoside transmembrane transport
Cellular component: apical plasma membrane; basolateral plasma membrane; plasma membrane; membrane; presynapse
Genetic constraint (gnomAD): Loss-of-function variants: 38 observed, 41.99 expected, observed/expected ratio (o/e) 0.9, 90% interval 0.7 to 1.19. The synonymous counts are far from expectation, so gnomAD's model fits this gene poorly and the ratio says little. Missense variants: 869 observed, 739.94 expected, observed/expected ratio (o/e) 1.17, 90% interval 1.11 to 1.24. Synonymous variants: 491 observed, 331.52 expected, observed/expected ratio (o/e) 1.48, 90% interval 1.38 to 1.6.
Homologues: Orthologues: chimpanzee SLC29A4 (99% identical), macaque SLC29A4 (90% identical), mouse Slc29a4 (87% identical), rat Slc29a4 (86% identical), guinea pig SLC29A4 (86% identical), dog SLC29A4 (86% identical), pig SLC29A4 (85% identical), zebrafish slc29a4a (64% identical), zebrafish slc29a4b (59% identical), Drosophila melanogaster Ent3 (40% identical). Paralogues in human: SLC29A3 (22% identical), SLC29A2 (21% identical), SLC29A1 (20% identical).
Diseases named in the same sentence as SLC29A4 in open-access papers:
SLC29A4 is named in the same sentence as 21 diseases in open-access papers, as found by Europe PMC text mining. Sharing a sentence is not in itself a finding about the gene and the disease. The quoted sentences say what the papers report.
autism spectrum disorder (4 papers, 2014 to 2020). A spectrum of developmental disorders that includes autism, and Asperger syndrome. "However, the contribution by SLC6A4 and SLC29A4 mutations in our study remained minor with respect to the whole population of autism spectrum disorders." (PMID 33294225, 2020).
type II diabetes (1 paper, 2022). "Functional polymorphisms in the human PMAT gene (SLC29A4) can affect treatment responses to metformin, a drug for type II diabetes management." (PMID 35741002, 2022).
SLC29A4 also shares sentences with these, for which no sentence is quoted: cancer (5 papers); tumor (5); autism (3); Anxiety (2); Alzheimer disease (1); arteriosclerosis (1); breast carcinoma (1); cerebrovascular disorder (1); chronic kidney disease (1); depression (1); endothelial dysfunction (1); Ewing sarcoma (1); Hypertension (1); ischemia (1); ischemic stroke (1); liver cancer (1); lymphoma (1); myocardial ischemia (1); Ureteral obstruction (1).